YTHDC1 (YTH N6-methyladenosine RNA binding protein C1)
Diseases named in the same sentence as YTHDC1 in open-access papers (continued):
Sharing a sentence is not in itself a finding about the gene and the disease.
liver cancer (5 papers, 2022 to 2025). An epithelial or non-epithelial malignant neoplasm that arises from the liver. "Further studies are needed to elucidate how YTHDC1 regulates immune-related mRNA trafficking and translation in liver cancer cells, as well as its broader impact on immune responses within the tumor microenvironment." (PMID 39911396, 2025). "We found that YTHDC1 knockdown also inhibited lipid droplet accumulation in liver cancer cells, indicating that YTHDC1 was a key protein in lipid metabolism by participating in RNA modification." (PMID 40180937, 2025). "Despite these promising findings, the precise molecular mechanisms through which YTHDC1 regulates liver cancer immunotherapy remain insufficiently understood and require further in-depth investigation." (PMID 39911396, 2025). "As a key m6A reader protein, YTHDC1 plays a crucial role in regulating the expression and function of immune-related genes in liver cancer." (PMID 39911396, 2025). "This dual function of YTHDC1 in both immune activation and immune evasion makes it a critical regulator of liver cancer progression and response to immunotherapy." (PMID 39911396, 2025). "In addition to its role in immune activation, YTHDC1 may also influence the expression of immune evasion-related genes within liver cancer cells, thereby altering the tumor’s resistance to immune attack." (PMID 39911396, 2025). "KIAA1429 increases the m6A methylation in 3′-UTR of the RND3 mRNA and decreases its stability via m6A reader YTHDC1 (YTH N6-methyladenosine RNA binding protein C1), and then down-regulates the RND3 expression level in liver cancer." (PMID 39456252, 2024).
Obesity (5 papers, 2021 to 2025). Accumulation of substantial excess body fat. "To determine whether Ythdc1-BKO mice are more susceptible to HFD-induced obesity, we fed Ythdc1-BKO and Ythdc1flox/flox mice with an HFD and monitored their body weights weekly." (PMID 40355558, 2025). "To assess whether Ythdc1 expression in iBAT is associated with obesity, we examined YTHDC1 protein levels in two mouse models of obesity: high-fat diet (HFD)-induced obesity and leptin receptor-deficient db/db mice." (PMID 40355558, 2025). "Furthermore, in human cohorts, the study found that the writers WTAP and VIRMA, the eraser ALKBH5, and reader proteins such as YTHDF1, YTHDF2, and YTHDC1 are associated with obesity by comparing gene expression of m6A regulators in adipose tissue between individuals with obesity and lean controls." (PMID 40428320, 2025). "“Writers” like METTL3 and METTL14 add m6A marks, “erasers” such as fat mass and obesity-associated protein (FTO), ALKBH5 remove them, and “readers” including YTHDF1, YTHDC1 recognize the marks, mediating functional outcomes." (PMID 40442779, 2025). "Ythdc1-BKO mice gained similar body weight to Ythdc1flox/flox mice during HFD feeding, indicating that Ythdc1-BKO mice are not more susceptible to HFD-induced obesity." (PMID 40355558, 2025). "In adipose tissue we observed that several m6A regulators (WTAP, VIRMA, YTHDC1 and ALKBH5) correlate with obesity and clinical variables." (PMID 34950106, 2021). "Neither Wtap-BKO nor Ythdc1-BKO mice promote HFD-induced obesity, which is likely attributed to the increased physical activity observed in both Wtap-BKO and Ythdc1-BKO mice." (PMID 40355558, 2025).
ovarian carcinoma (5 papers, 2021 to 2025). A malignant neoplasm originating from the surface ovarian epithelium. "The role of PIK3R1 in ovarian cancer was further explored by overexpressing PIK3R1 in YTHDC1 deficient SKOV3 and A2780 cells." (PMID 37781028, 2023). "In the current study, we confirmed that PIK3R1 is significantly lowly expressed in ovarian cancer, thereby ameliorating the tumor-promoting property of YTHDC1 deficiency." (PMID 37781028, 2023). "RNA-seq data showed that metabolic pathway, especially N-glycan biosynthesis, was involved in ovarian cancer development with YTHDC1 knockdown." (PMID 37781028, 2023). "To examine the potential role of the m6A reader YTHDC1 in the progression of ovarian cancer, we firstly analyzed YTHDC1 expression level in ovarian cancer." (PMID 37781028, 2023). "In this study, we demonstrated that YTHDC1 undergoes a significant reduction in its expression in ovarian cancer." (PMID 37781028, 2023). "EdU and CCK-8 assays indicated that the growth of ovarian cancer cells was remarkably suppressed with YTHDC1 upregulation." (PMID 37781028, 2023). "Our findings also demonstrate the role of YTHDC1 as a tumor suppressor in ovarian cancer development." (PMID 37781028, 2023). "In this study, we aimed to unravel the functions of m6A modifications (especially the reader YTHDC1) in regulating ovarian cancer progression." (PMID 37781028, 2023). "Our analysis using the GEPIA and Oncomine database revealed that the expression of YTHDC1 was remarkably lower among ovarian cancer tissues as compared to normal tissues of the ovary." (PMID 37781028, 2023). "In vitro and in vivo evaluation of the function of YTHDC1 in ovarian cancer, we first established stable ovarian cancer cell lines of YTHDC1-overexpressing (OE-YTHDC1)." (PMID 37781028, 2023). "Altogether, these findings confirm the important function of YTHDC1 in inhibiting the progression of ovarian cancer both in vitro and in vivo." (PMID 37781028, 2023). "Mechanistically, low expression of YTHDC1 promotes ovarian cancer tumorigenesis via PIK3R1/STAT3/GANAB axis." (PMID 37781028, 2023). "We found decreased YTHDC1 and increased RBM15 expressions were associated with ovarian cancer cell metastases and HNRNPC was a predictor of paclitaxel resistance." (PMID 33225598, 2021). "GSEA analysis demonstrated that the expressions of METTL3, YTHDC1, RBM15B, HNRNPC, IGF2BP2, RBMX, and ZC3H13 were correlated with a higher number of multiple Hallmark pathways in ovarian cancer." (PMID 33225598, 2021). "Herein, we first observed that YTHDC1 underwent significant downregulation in ovarian cancer." (PMID 37781028, 2023). "However, the biological role and mechanism of m6A reader YTH Domain Containing 1 (YTHDC1) in ovarian cancer progression remain inadequately understood." (PMID 37781028, 2023). "Our results showed that the overexpression of YTHDC1 could inhibit the progression of ovarian cancer both in vivo and in vitro." (PMID 37781028, 2023). "In summary, the expression of YTHDC1 was found to be downregulated in ovarian cancer." (PMID 37781028, 2023). "Additionally, we observed by IHC staining that there was a significant decrease of YTHDC1 protein level in ovarian cancer tissues as compared to benign ovarian tissues of humans." (PMID 37781028, 2023). "Moreover, the GEO datasets also confirmed that there was significant downregulation of the YTHDC1 mRNA in the case of ovarian cancer (GSE36668) and low expression in ascites ovarian cancer compared to primary ovarian cancer (GSE73168)." (PMID 37781028, 2023). "Overexpression of YTHDC1 inhibited ovarian cancer development both in vivo and in vitro." (PMID 37781028, 2023). "Thus, our data suggest that PIK3R1 as a crucial downstream target of YTHDC1 for inhibiting the progression of ovarian cancer." (PMID 37781028, 2023).
ovarian carcinoma (continued). "Furthermore, GEPIA database analysis showed that only four genes, PIK3R1, JUNB, RHOBTB2, and SLC25A37, were expressed at low level in ovarian cancer and were correlated positively with YTHDC1." (PMID 37781028, 2023). "Collectively, these results indicate that PIK3R1 is a direct target of YTHDC1 in ovarian cancer." (PMID 37781028, 2023). "Herein, we show that YTHDC1 has a low expression in ovarian cancer, suggesting that YTHDC1 may be a tumor suppressor gene." (PMID 37781028, 2023). "Thus, YTHDC1 could be a prospective candidate for the development of a predictive biomarker and a promising target gene for the treatment of ovarian cancer." (PMID 37781028, 2023). "Therefore, we examined whether YTHDC1 regulated N-glycan biosynthesis to affect ovarian cancer progression." (PMID 37781028, 2023). "Therefore, we concluded that YTHDC1 may play the important role of a tumor repressor in ovarian cancer progression, which sheds light on the targeted therapy for ovarian cancer." (PMID 37781028, 2023). "However, the regulation and function of m6A reader YTHDC1 in response to ovarian cancer are largely unknown." (PMID 37781028, 2023). "However, the molecular mechanism by which YTHDC1 recognizes and regulates the expression of its target genes is still unknown in the development of ovarian cancer." (PMID 37781028, 2023). "Further investigation of the underlying molecular mechanism employed by YTHDC1 in the progression of ovarian cancer was performed by RNA-seq analysis in the SKOV3 and A2780 cells with YTHDC1 knockdown." (PMID 37781028, 2023). "As a result, YTHDC1 knockdown significantly promoted ovarian cancer progression in vivo and in vitro and GANAB knockdown markedly suppressed ovarian cancer progression in vivo and in vitro, however, silencing GANAB abrogated shYTHDC1-induced tumor promotion." (PMID 37781028, 2023). "We found that a decrease in YTHDC1 and an increase in RBM15 expressions were correlated with ovarian cancer cell metastases." (PMID 33225598, 2021). "For example, the expression of HNRNPA2B1 was positively correlated with the expressions of IGF2BP3, YTHDC1, YTHDF2, RBM15, and ZC3H13 in ovarian cancer." (PMID 33225598, 2021). "We also noticed that decreased expression of YTHDC1 and increased expression of RBM15 were correlated with the status of ovarian cancer cell metastasis (GSE73168 and GSE30587)." (PMID 33225598, 2021). "Moreover, a lower expression level of PIK3R1 induced by YTHDC1 knockdown leads to activation of STAT3 signaling, which further promotes GANAB expression in the nucleus, followed by an increase of GANAB-mediated N-glycan biosynthesis in ovarian cancer cells, which promotes ovarian cancer progression." (PMID 37781028, 2023).
triple-negative breast carcinoma (5 papers, 2022 to 2025). An invasive breast carcinoma which is negative for expression of estrogen receptor (ER), progesterone receptor (PR), and human epidermal growth factor receptor 2 (HER2). "This study aims to uncover the essential role and the underlying molecular mechanism(s) of the m6A reader YTHDC1 in promoting triple negative breast cancer (TNBC) metastasis." (PMID 35966596, 2022). "When YTHDC1 is overexpressed in triple-negative breast cancer, there is a notable increase in lung metastases in vivo." (PMID 38745192, 2024). "Notably, YTHDC1 is vital for triple-negative breast cancer progression because it increases cancer cell survival and TGF-β-mediated EMT via SMAD3 to promote distant metastasis, highlighting the therapeutic potential of targeting the YTHDC1–m6A–SMAD3 axis." (PMID 40986143, 2025). "Finally, the YTHDC1 gene, which recognizes N6-methyladenosine (m6A) RNA modifications, has been identified as a crucial gene related to the metastasis of triple-negative breast cancer in humans." (PMID 41168812, 2025).
viral infection (5 papers, 2018 to 2024). "We determined whether the NSA530C mutation altered the binding efficiency to YTHDC1 under virus infection." (PMID 37053288, 2023). "Here, we identify YTHDC1 as a novel negative regulator of RSV viral infection by downregulating the expression of host cell RSV entry receptor CX3CR1." (PMID 38793659, 2024). "In the context of viral infection, research has shown, that YTHDC1 is involved in splicing of genes important for the lytic replication." (PMID 36050747, 2022). "Among m6A readers, YTHDC1 was upregulated by viral infection (three of six experiments), while the expression levels of YTHDF1 and YTHD2 were not affected." (PMID 34502037, 2021). "Considering YTHDC1 is an m6A reader protein that binds to mRNA, we next determined whether YTHDC1 targets the NS mRNA, resulting in the decrease of NS mRNA splicing under virus infection." (PMID 37053288, 2023).
asthma (4 papers, 2021 to 2025). "By applying univariate logistic regression and LASSO Cox regression models, they identified YTHDF3 and YTHDC1 as key m6A regulators significantly associated with severe asthma." (PMID 41008562, 2025). "We examined the expression data of the 16 difference‐expressed genes using univariate logistic regression to identify the potential m6A regulators, and two regulators (YTHDF3 and YTHDC1) were found to be associated with severe asthma." (PMID 34647423, 2021). "They found abnormal expression of YTHDF3 and YTHDC1 in many severe asthma patients, suggesting alterations in the immune microenvironment and influencing eosinophil activity relevant to severe asthma." (PMID 39135292, 2024). "Correlation analyses also revealed strong interactions between YTHDF3, YTHDC1, and other m6A machinery components, indicating that their cooperative activity may contribute to immune dysregulation and the pathogenesis of severe asthma." (PMID 41008562, 2025). "Considered together, the m6A regulators YTHDF3, YTHDC1, WTAP, FTO, METTL3, and ETTL14 may have a significant effect on the prognosis of asthma, but studies on m6A methylation, severe asthma, and the prognosis of asthma are still in the initial stage and require further exploration by researchers." (PMID 39108751, 2024).
atherosclerosis (4 papers, 2022 to 2025). A disease characterized by the build-up of fatty material and calcium deposition in the arterial wall resulting in partial or complete occlusion of the arterial lumen. "Additionally, investigations into atherosclerosis have revealed that a reduction in YTHDC1 expression may exacerbate inflammatory responses, accelerate the expression of senescence-related genes, and thereby facilitate the development of atherosclerosis." (PMID 40198960, 2025). "Accordingly, we consider that low expression of YTHDC1 leads to elevated RGN expression by promoting macrophage inflammation, which increases apoptosis in vascular smooth muscle cells and ultimately exacerbates atherosclerosis." (PMID 38168909, 2024).
diabetes (4 papers, 2024 to 2025). "YTHDC1‐mediated m6A methylation regulates diabetes‐induced RVECs dysfunction, YTHDC1‐CDK6 signaling axis could be therapeutically targeted for treating DR." (PMID 39931738, 2025). "Similarly, both m6A and YTHDC1 levels were reduced in patients with T2DM, and deletion of Ythdc1 in βKO mice caused glucose intolerance and diabetes due to decreased insulin secretion." (PMID 41585810, 2025). "YTHDC1-mediated m6A methylation regulates diabetes-induced RVECs dysfunction." (PMID 38978074, 2024). "YTHDC1 was found to be down-regulated in islet β-cells in T2DM, and β-cell–specific deletion of Ythdc1 resulted in β-cell failure and diabetes." (PMID 41585810, 2025).
myeloid leukemia (4 papers, 2022 to 2024). A clonal proliferation of myeloid cells and their precursors in the bone marrow, peripheral blood, and spleen. "In myeloid leukemia, nuclear YTHDC1-m6A condensates (nYACs) enable YTHDC1 to protect m6A-modified mRNAs from degradation and maintain cell survival and an undifferentiated state." (PMID 38560499, 2024). "The RBFOX2/m6A/RBM15/YTHDC1/PRC2 axis plays an important role in myeloid leukaemia, with downregulation of RBFOX2 notably inhibiting acute myeloid leukaemia (AML) cell survival/proliferation and promoting myeloid differentiation of AML cells." (PMID 37640841, 2023). "Furthermore, we found that this RBFOX2/m6A/RBM15/YTHDC1/PRC2 axis plays a critical role in myeloid leukaemia." (PMID 37640841, 2023). "The ability of YTHDC1 to form phase separated nuclear condensates, which has been shown to stabilize m6A-modified RNAs in myeloid leukemia cells, may play a role in stabilizing HOTAIR, providing a large reservoir that leads to aberrant targeting of genomic loci in cancer." (PMID 36441764, 2022). "In myeloid leukemia, m6A is found to be required for YTHDC1 to undergo LLPS, generating nuclear YTHDC1–m6A condensates to maintain cell survival and myeloid leukemic undifferentiated state." (PMID 39006762, 2024).
rhabdomyosarcoma (4 papers, 2022 to 2023). A rare aggressive malignant mesenchymal neoplasm arising from skeletal muscle. "Interaction between DDX5 and YTHDC1 promotes the splicing of pre-mRNA into mature circRNA in rhabdomyosarcoma cells." (PMID 38062349, 2023). "Recently, it was proven that the circRNA circ-ZNF609, which requires YTHDC1 for its back-splicing reaction, increases in pathological conditions, such as rhabdomyosarcoma." (PMID 35563766, 2022). "In line with the observation that YTHDC1/DDX5 depletion reduces RMS proliferation, our results provide proteins and RNA candidates for the study of rhabdomyosarcoma tumorigenicity." (PMID 37019933, 2023).
sarcoma (4 papers, 2021 to 2024). A usually aggressive malignant neoplasm of the soft tissue or bone. "Kaplan–Meier analysis using data derived from the TCGA cohort also revealed that low expression of the YTHDC1 was associated with a good prognosis in patients with sarcoma." (PMID 38233839, 2024). "Moreover, METTL3 and m6A binding protein YTHDC1 are responsible for DSBs HR repair in human sarcoma U2OS cells; METTL3 depletion enhances the sensitivity to DNA-damaging therapy." (PMID 35279688, 2022). "The results showed that fused in sarcoma (FUS), aconitase 1 (ACO1), and YTH domain containing 1 (YTHDC1) motifs have specific miR-18b binding sites." (PMID 34853307, 2021).
bladder tumor (3 papers, 2021 to 2023). "We next tested the degree of DNA damage in bladder tumour sections with different YTHDC1 expression, and cells that were treated with cisplatin." (PMID 37070134, 2023).
brain infarct (3 papers, 2020 to 2025). "The forced expression of YTHDC1, a nuclear m6A reader protein, decreased brain infarct volume and promoted neuronal cell survival by facilitating Akt phosphorylation through degrading Pten mRNA, demonstrating an opposite role to YTHDF1." (PMID 40591025, 2025). "Forced expression or knockdown of YTHDC1 could decrease or increase brain infarct volume, respectively." (PMID 33188203, 2020).
dilated cardiomyopathy (3 papers, 2021 to 2024). Cardiomyopathy which is characterized by dilation and contractile dysfunction of the left and right ventricles. "Combining MeRIP-seq, RIP-seq of YTHDC1 and mRNA-seq revealed that correct splicing ofTitin (TTN), the most commonly known genetic cause of dilated cardiomyopathy, is regulated by YTHDC1, likely in a m6A-dependent manner." (PMID 39574165, 2024). "A recent study found that depletion of YTHDC1 induced dilated cardiomyopathy phenotype and significantly prolonged the relaxing time of cardiomyocytes in mice." (PMID 36267414, 2022). "Here, we report that the defect in YTHDC1 but not other YTH family members contributes to dilated cardiomyopathy (DCM) in mice." (PMID 34716659, 2021). "YTHDC1, but not other YTH family readers, is related to dilated cardiomyopathy (DCM)." (PMID 39574165, 2024).